CP (ceruloplasmin)
Diseases named in the same sentence as CP in open-access papers (continued):
Sharing a sentence is not in itself a finding about the gene and the disease.
liver fibrosis (11 papers, 2013 to 2025). "Another key point is that CP variants are independently linked to hyperferritinemia, hepatic iron overload, and advanced liver fibrosis in patients with MASLD." (PMID 40870862, 2025). "In this study, we investigated associations between serum CP levels and inflammation grade and liver fibrosis stages in patients with chronic hepatitis B-virus related liver disease." (PMID 24282481, 2013). "CCl4-induced fibrosis was significantly attenuated by treatment of mice with CP-FUS-NLS, showing that CP-FUS-NLS exerts antifibrotic action in a mouse model of liver fibrosis." (PMID 38488009, 2024). "In male HBV-related cirrhotic patients, serum ceruloplasmin levels were inversely correlated with hepatic fibrosis, because ceruloplasmin is synthesized in the liver." (PMID 32674425, 2020). "In a previous report, we demonstrated that microRNA-125b in exosomes released from CP-MSCs repressed Hedgehog (Hg) signaling, which promotes hepatic fibrosis, indicating that microRNA-mediated Hh pathways assisted with liver regeneration by CP-MSCs." (PMID 33133194, 2020). "Liver fibrosis and increased expression of type I collagen and α-smooth muscle actin in CCl4-treated rats were reduced after CP-MSC transplantation, which suggested that CP-MSCs have antifibrotic effects." (PMID 29250120, 2017). "ROC curve analysis was performed and the optimal cut-off CP value was determined for identifying stages of inflammation and liver fibrosis." (PMID 24282481, 2013). "Future study will include a larger gender-matched cohort, prospective design and further training of CP alone as a marker of liver fibrosis in CHB and of the related APPCI model, especially to determine why CP levels decline in CHB patients and to further validate the model." (PMID 24282481, 2013). "Taken together, those results support our hypothesis that CP-MSCs release exosomes or MVs containing miRNA-125b into target cells, such as Hh-responsive HSCs, and hinder the activation of Hh signaling by inhibiting Smo expression, eventually alleviating hepatic fibrosis." (PMID 26370741, 2015). "The increase of serum copper levels in experimental hepatic fibrosis and in patients with liver cirrhosis or ALD could be due to the elevation of ceruloplasmin in the serum." (PMID 30679730, 2019). "The degree of liver fibrosis in the BDL groups with or without transplantation was increased at all times (p < 0.05), whereas the degree of fibrosis was significantly decreased in the CP-MSC transplantation group compared to those of the BDL and WI-38 groups until 2 weeks (p < 0.05)." (PMID 34685509, 2021).
Stroke (11 papers, 2013 to 2024). Sudden impairment of blood flow to a part of the brain due to occlusion or rupture of an artery to the brain. "Using this model, both CP-Tg and WT mice were tested for resistance to thrombosis, one of the major leading causes of stroke and heart arrest." (PMID 29374184, 2018). "The recent research has indicated that increased ceruloplasmin concentrations were associated with an increased risk of myocardial infarction and stroke." (PMID 23781119, 2013). "The causes of death in the low ceruloplasmin group were: infectious events (n = 4), vasculitis relapse (n = 1), thromboembolic events (n = 2, i.e., stroke or acute coronary syndrome) and unknown cause (n = 3)." (PMID 39388433, 2024). "Finally, ceruloplasmin deficient mice are more vulnerable to rotenone and stroke." (PMID 23536801, 2013). "Evaluated carboxyhemoglobin levels are associated with increased levels of inflammation‐sensitive proteins, such as fibrinogen, haptoglobin, and ceruloplasmin, all of which have established links with cardiovascular disease and stroke." (PMID 38376055, 2024). "High serum CP levels have been found in patients with arteriosclerosis, unstable angina, stroke and MI." (PMID 33096845, 2020). "By the PRM validation, IGHA1, LRG1, IGHV3-64D, and CP may be biomarkers of neurological recovery after stroke." (PMID 36959823, 2023). "In addition, IGHA1, LRG1, IGHV3-64D, and CP are upregulated in patients with ischemic stroke and downregulated after rehabilitation, which may be used as biomarkers to monitor neurological impairment and recovery after stroke." (PMID 36959823, 2023). "Our study identified four proteins (ceruloplasmin, SERPINA1, vWF, and F13B) that commonly differentiated total stroke, IS, and ICH from healthy control subjects." (PMID 36237606, 2022). "Four proteins [ceruloplasmin, alpha-1-antitrypsin (SERPINA1), von Willebrand factor (vWF), and coagulation factor XIII B chain (F13B)] commonly differentiated total stroke, IS, and ICH from healthy control subjects." (PMID 36237606, 2022). "Although ceruloplasmin was not upregulated in response to RIC in our experiments, recent findings support the role of this protein in ameliorating stroke outcomes." (PMID 36291633, 2022).
type 2 diabetes (11 papers, 2013 to 2025). "Specifically, high Cd exposure is associated with an increased risk of type 2 diabetes, and elevated levels of total Cu and ceruloplasmin have been found in patients with type 1 diabetes." (PMID 38389043, 2024). "Our recent work has demonstrated the mutually compensatory roles of HEPH and CP in adipose tissue, and how loss of both MCFs results in adipocyte iron deposition, insulin resistance and type 2 diabetes." (PMID 29883959, 2018). "A 27-year-old female patient with liver cirrhosis and maturity-onset diabetes of the young was found to have normal serum ceruloplasmin (25.9, 20–60 mg/dL) and copper levels (17.81, 12.6–23.6 μmol/L)." (PMID 40629618, 2025). "Ceruloplasmin was demonstrated to be an independent predictor for the progression of diabetic nephropathy in patients with type 2 diabetes and is a potential biomarker of diabetic retinopathy." (PMID 32831070, 2020). "In a prospective study, fibrinogen, complement C3, C4 and haptoglobin were associated with insulin resistance and incident type 2 diabetes, but not α1-antitrypsin, ceruloplasmin or orosomucoid." (PMID 29258604, 2017). "In addition, elevated iron and copper ion concentrations were reported to occur in the plasma of type II diabetics, probably released by metal storage proteins such as ferritin and ceruloplasmin, respectively." (PMID 23483930, 2013). "Ceruloplasmin, another acute-phase protein produced in the liver that plays a role in copper metabolism and may have a role in the pathogenesis of metabolic diseases such as type 2 diabetes, decreased significantly in the semaglutide group but not in the empagliflozin group." (PMID 36982786, 2023). "Once hyperinsulinemia is confirmed by detecting FINS in a patient with insulin or insulin analog-treated type 2 diabetes, the FINS/CP ratio should be calculated and, subsequently, a more precise assay such as RIA, or PEG precipitation, carried out." (PMID 37324170, 2023).
atherosclerosis (10 papers, 2017 to 2025). A disease characterized by the build-up of fatty material and calcium deposition in the arterial wall resulting in partial or complete occlusion of the arterial lumen. "The weakening of the antioxidant defense system of the body, as evidenced by a decrease in catalase activity and the serum ceruloplasmin level, and an increased risk of atherosclerosis due to the hypoalphacholesterolemia were demonstrated." (PMID 38108959, 2024). "A comprehensive understanding of the CP role in copper metabolism, lipoprotein oxidation and atherosclerosis development, in other words cardiovascular and metabolic diseases, constitutes an important area of research." (PMID 40990027, 2025). "The effect of CP involved in cuproptosis-related atherosclerosis and the functions of ceruloplasmin as a mediator in the development of coronary heart disease need further investigation to explore the possible mechanism." (PMID 37324184, 2023). "The probable relationship between the CP concentration in serum and the incidence of atherosclerosis and other cardiovascular conditions was first suggested in the 1950s." (PMID 33096845, 2020). "High ceruloplasmin/copper levels have been reported in patients with atherosclerosis and myocardial infraction." (PMID 30147446, 2018). "In humans, expression of the ferroxidases hephaestin and ceruloplasmin was reduced in atherosclerosis." (PMID 28251312, 2017). "Although Arg1 and CP are associated with several pathological processes, e.g., increased cardiovascular risk, immune-mediated reactions, and atherosclerosis, the results show that these enzymes do not seem to be associated with the severity of bruxism." (PMID 40990027, 2025). "Furthermore, an increase in Cu concentration, mainly due to an increase in oxidase activity and ceruloplasmin levels, has been observed in both serum and arterial walls in atherosclerosis." (PMID 37571395, 2023). "Ceruloplasmin is a specific copper-containing plasma glycoprotein that belongs to the acute phase proteins and has pro- and anti-inflammatory properties, therefore its role in atherosclerosis is contradictory." (PMID 36361589, 2022). "In the training dataset GSE97210, SLC31A1, ATP7A, SLC31A2, UBE2D1, CP and FDX1 were highly expressed while LOXL2, COA6 and SOD1 were lowly expressed in the atherosclerosis group as showed in the bar charts." (PMID 37324184, 2023).
glaucoma (10 papers, 2012 to 2025). Increased pressure in the eyeball due to obstruction of the outflow of aqueous humor. "Recently, the two forms of CP were observed in the eyes of patients with high intraocular pressure and established glaucoma: the holo-CP (six copper atoms per molecule) and the apo-CP (the protein without the copper)." (PMID 40650085, 2025). "Immunoglobulin serology for CP is significantly higher in patients with glaucoma compared to controls." (PMID 30050429, 2018). "In monkeys with experimental glaucoma, microarray assay has demonstrated ceruloplasmin upregulation and immunohistochemical studies have localized the ceruloplasmin to Müller cells." (PMID 23825457, 2013). "Ceruloplasmin has been found to be upregulated in the retina in multiple pathological conditions including light damage, optic nerve crush, glaucoma, and diabetes." (PMID 23825457, 2013). "In human retinas with glaucoma, there are increased ceruloplasmin levels in the inner plexiform layer, ganglion cell layer, and nerve fiber layer compared with controls by immunohistochemistry." (PMID 23825457, 2013). "Taken together, the up regulation of ceruloplasmin protein levels involved in early myopia found here for the first time may be triggered by initial ocular enlargement stress similar to findings in glaucoma." (PMID 33946922, 2021). "Moreover, up-regulation of CP was also found in most human eyes with glaucoma and localized to the Muller cells within the retina and in the area of the inner limiting membrane." (PMID 33946922, 2021). "In previous glaucoma studies, by RT-PCR and immunoblotting analysis, CP mRNA and CP protein were up-regulated in the retinas of glaucomatous DBA/2 mice, which indicated triggering by the IOP stress and then lead to retinal ganglion cell (RGC) loss in the retina." (PMID 33946922, 2021). "The expression of FT, CP, and TF was increased in monkey and rat glaucoma models." (PMID 32183063, 2020). "Here we test the hypothesis that CP-AMPARs contribute to RGC death due to elevated Ca2+ influx in glaucoma." (PMID 24608178, 2014). "Furthermore, our data provide evidence that ADAR2 and CP-AMPARs may contribute to RGCs dysfunction due to elevated Ca2+ influx in glaucoma." (PMID 24608178, 2014). "In fact, the slow time course of excitotoxicity that is predicted by the CP-AMPAR model, compared with the NMDA receptor model, is more consistent with the observed time course in glaucoma patients." (PMID 24608178, 2014).
liver cancer (10 papers, 2019 to 2024). An epithelial or non-epithelial malignant neoplasm that arises from the liver. "Previous study has reported that ferroptosis activators (Erastin and RSL3) can promote ferroptosis by inhibiting CP expression in liver cancer 15, our study indicated similar results." (PMID 38385087, 2024). "It was found that CP inhibited the tumor growth and metastasis of HBV-associated HCC in both mice liver cancer xenograft and zebrafish xenotransplantation models." (PMID 34168559, 2021). "Next, CP assay revealed that SMAD7 can bind to endogenous YAP in the liver cancer cell lines overexpressing SMAD7-Flag." (PMID 31711043, 2019). "In addition, the IMF deposition group showed higher AFP, INR, and CP score, and lower sodium and albumin levels, which are markers of the severity of liver cancer." (PMID 31888500, 2019). "Several cfRNAs specific to liver cancer are genes known to be specifically expressed in the liver (TF, HRG, CP, and FGA)." (PMID 35816095, 2022). "Sub-stratification analyses were performed using CP and ALBI and in subgroups determined by United Network for Organ Sharing (UNOS) or Barcelona Clinic Liver Cancer (BCLC) staging." (PMID 31238514, 2019).
lung adenocarcinoma (10 papers, 2014 to 2024). A carcinoma that arises from the lung and is characterized by the presence of malignant glandular epithelial cells. "CP is a well-known copper-binding protein, which has been associated with cancer development and suggested as a useful biomarker for lung adenocarcinoma." (PMID 35174082, 2022). "CP is produced heterotopically in lung adenocarcinoma cells, and its expression correlates with tumor progression." (PMID 39165641, 2024). "Together, these findings indicate that CP expression is higher in advanced-stage lung adenocarcinoma." (PMID 32708433, 2020). "CP can be heterotopically generated in lung adenocarcinoma (LUAD) cells." (PMID 34413268, 2021). "The concentration of ceruloplasmin was reduced by approximately three orders of magnitude in patients with neurological disorders compared to healthy volunteers, and those of gelsolin isoform 1 and complement factor H were abruptly reduced in patients with lung adenocarcinoma." (PMID 36614211, 2023). "Interestingly, ceruloplasmin level is significantly higher in lung adenocarcinoma than squamous cell carcinoma, and in female than in male, which could not be explained by smoking history." (PMID 28088789, 2017). "In the high expressing human lung adenocarcinoma H2126 cell-line, the complete promoter with exon 2 and intron 2 construct (CP-E2I2-Luc, p = 0.003) and the promoter alone construct (CP-Luc, p = 0.006), were able to significantly increase luciferase expression compared to pGL3 Basic (data not shown)." (PMID 24475248, 2014). "Importantly, three of the non-COSMIC predictors included in the top ten for the C2.CP collection (DST, FRG1B and BAGE2) are also in the top ten for the C6 collection and none of the three has an established association with lung adenocarcinoma." (PMID 30541428, 2018).
preeclampsia (10 papers, 2011 to 2025). Preeclampsia is a hypertensive disorder of pregnancy that is characterized by new-onset hypertension with proteinuria presenting after 20 weeks of gestation, and depending on mild or severe forms may initially present with severe headache, visual disturbances, and hyperreflexia. "We identified multiple activated hypoxia pathways from early-onset preeclampsia placentas and found that CP is upregulated in preeclampsia and downregulated in placenta accreta specifically in the decidual cell population." (PMID 41141914, 2025). "CP levels are increased in placentas of severe preeclampsia, localizing to the intervillous space and syncytiotrophoblasts, and CP increases in blood with worsening clinical features of preeclampsia." (PMID 41141914, 2025). "Ceruloplasmin (CP) is predominantly expressed in the syncytiotrophoblast, with its expression notably increased under hypoxic conditions such as those present in preeclampsia." (PMID 41444673, 2025). "Women with severe preeclampsia had considerably greater Cu and ceruloplasmin levels than patients with mild (81.2 μg/dL) and severe preeclampsia (160.2 μg/dL)." (PMID 34835995, 2021). "Another study has reported a relation between severe preeclampsia and ceruloplasmin, and copper level." (PMID 34835995, 2021). "Several proteins including ceruloplasmin and serpin A7 are upregulated in maternal urine before the diagnosis of preeclampsia and potentially fetal growth restriction." (PMID 34682802, 2021). "Abnormal levels of ceruloplasmin have been found in blood and/or in amniotic fluid during pregnancies which resulted in such conditions as spontaneous abortions, preeclampsia, and Klinefelter's syndrome." (PMID 21765892, 2011). "CP, a copper-carrying protein involved in iron metabolism, serves a dual role - both as a protective mechanism against oxidative stress through its ferroxidase activity and as a marker of the inflammatory response characteristic of preeclampsia." (PMID 41444673, 2025). "Although late-onset preeclampsia is not as strongly associated with placental vascular dysfunction as early-onset preeclampsia, genes such as CP, IGFBP7, CDH13, ROBO1, UNC5C, NRXN3, and ITGA1 suggest subtle changes in angiogenic pathways." (PMID 41444673, 2025). "Interestingly, the case of fetal growth restriction without preeclampsia would have been detected with ceruloplasmin but not with serpin A7." (PMID 34682802, 2021).
co-infection (9 papers, 2012 to 2024). "maxima sporulated oocysts/bird on d 15); CP (challenged with 1.0 × 108 CFUs/bird of C. perfringens on d 19 and d 20); and EM + CP (challenged by co-infection of E. maxima and C. perfringens as described)." (PMID 39759108, 2024). "The level of total protein, gamma globulins, the activity of lysozyme and ceruloplasmin, as well as the metabolic activity and potential killing activity of phagocytes were measured: 0, 24 h, 72 h, 7 days, 14 days, and 21 days after co-infection." (PMID 34359116, 2021). "Co-infection of BrYV and PEMV 2 appears to be beneficial to BrYV by facilitating the tremendous increase in BrYV RNA and CP, and PEMV 2 is very likely the cause of these synergistic effects." (PMID 28345652, 2017). "Severe-ApCAP group = 97/215 (45.12%), MP = 84/97 (86.60%), CP = 6/97 (6.19%), LP = 7/97 (7.22%); Co-infection with bacteria = 27.83% (27/97): SP = 14/27, HI = 8/27, co-infection with respiratory viruses = 13.4% (13/97): RSV = 2/13, INF = A/B virus = 3/13, AdV = 4/13, RV = 4/13." (PMID 35866332, 2022). "The co-infection of the sweet cherry trees with different LChV1 isolates was confirmed by RT-PCR amplification and RFLP analysis of the amplified CP gene." (PMID 30037079, 2018). "In this study, we found that co-infection of BrYV and PEMV 2 produced severe symptoms and increased the accumulation of BrYV RNAs and CP in N. benthamiana plants." (PMID 28345652, 2017). "The co-infection with different HPV types (HPV-16 and HPV-23) was observed only in one sample, B32, which was detected by GP and CP primer sets." (PMID 22566779, 2012). "In our study, we are confident that these were co-infections and not secondary infections because the anti-MP and -CP serologic tests performed within 48 h of the patients’ admissions showed IgM titers above the cut-off values." (PMID 36014055, 2022). "Non-severe ApCAP = 118/215 (54.88%), MP = 106/118 (89.83%), CP = 7/118 (5.93%), LP = 5/118 (4.24%); Co-infection with bacteria = 9.3% (11/118): SP = 4/118, HI = 4/118, co-infection with respiratory viruses = 5.1% (6/118): RSV = 0, INF A/B virus = 0, AdV = 0, RV = 4/6, Other viruses = 2/6." (PMID 35866332, 2022). "As co-infection increased the accumulation of 21- and 22-nt M-vsiRNAs, the hotspots distributed in the (+)- and (−)-sense strands of MCMV genome were both increased in co-infected maize plants, which mainly located in the P32/P50, P31 and CP coding regions and the 3′-UTR region." (PMID 26864602, 2016).